SMAD2 (SMAD family member 2)
Diseases named in the same sentence as SMAD2 in open-access papers (continued):
Sharing a sentence is not in itself a finding about the gene and the disease.
cancer (continued). "Screening of several TNBC cell lines showed altered Smad2 and Smad3 protein levels compared to normal mammary epithelial cells, suggesting the possibility that it could play an important role in the escape of cancer cells from TGF-β mediated growth inhibition." (PMID 31798766, 2019). "Indeed, the silencing of hMENA isoforms in PDAC invasive cancer cell lines abrogated SMAD2 phosphorylation and its nuclear localization, impairing the TGFβ-mediated EMT, suggesting that hMENA may control the activity of this and other transcription factors." (PMID 29907768, 2018). "Indeed, addition of recombinant inhibin α into the CM from miR-218-overexpressing cells reversed the activation of SMAD2/3 phosphorylation in recipient cancer cells, whereas adding neutralizing antibody against inhibin α into the CM to treat MC3T3 cells led to de-repression of SMAD2/3 signaling." (PMID 30348200, 2018). "However, although Smad2/3 may be absolutely required for TGFβ1-induced EMT in malignant tumors, there are also Smad-independent TGFβ1 pathways involved in EMT." (PMID 30174709, 2018). "Therefore, EGF could induce EMT and cancer cell invasion in MDA-MB-231 cells through the ERK1/2-phospho-Smad2/3-Snail signaling pathway." (PMID 27829223, 2016). "Interestingly, a previous study in a cancer cell line has shown that CDK4/6 could control the transcriptional activity of Smad2/3." (PMID 24074866, 2013). "Using A549 carcinoma epithelial cells as an in vitro model, we found that treatment with sorafenib in during TGF-β1-induced EMT resulted in a loss of active histone markers (H3K4me3 and/or H3K9ac) at the promoters of TGF-β1, Smad2/3 and downstream EMT mediators such as Snail and Slug." (PMID 23741434, 2013). "Furthermore, while Smad2 mutations in cancer have been described, no mutations in Smad3 or p21 have yet been reported." (PMID 22995475, 2012). "Since strategies for therapeutic targeting of the TGF-β signalling pathway are being pursued, revealing the identity of factors that modulate the relative activation of Smad2 or Smad3 in the TGF-β response may provide target(s) for more effective strategies for cancer therapy." (PMID 21624123, 2011). "TIPE2, a member of the same family, suppresses OVCA metastasis and epithelial–mesenchymal transition by interacting with SMAD2, indicating that our findings need to be experimentally validated for the role of TIPE3 in promoting cancer." (PMID 40343258, 2025). "Elevated EMP1 inhibits the interference of SMAD7 with SMAD2/3 activity by promoting the binding of VASP to SMAD7, ultimately activating the TGF-β/Smads signaling pathway-induced cancer cell invasiveness." (PMID 41285728, 2025). "The results indicate that WSG can exert anti-cancer effects by reducing the phosphorylation levels of Akt, ERK1/2, FAK, and Smad2." (PMID 40507156, 2025). "Direct effects of TGFβ on cancer cells’ chemoresistance are mediated by the TGF-β/SMAD pathway and miRNAs targeting components of the TGF-β pathway (SMAD2, SMAD3, SMAD4)." (PMID 39518142, 2024). "There was a greater difference in the expression of SMAD2, SMAD3, SMAD4, SMAD5, and SMAD9 between cancer and normal samples." (PMID 38514720, 2024).
cancer (continued). "An analysis with Reactome showed significant enrichment of SMAD2/3 and SMAD4 MH2 Domain Mutants in Cancer (p-value < 0.01)." (PMID 39484215, 2024). "EMT is a critical phase in the early stages of cancer metastasis and is controlled by signaling pathways such as STAT3 and Smad2/3." (PMID 39768811, 2024). "For example, in the DLX4 gene module, connections among DLX4, the known cancer gene ABL1, and four candidate AML genes (SP1, FYN, GRB2, and SMAD2) co-occurred in multiple patients." (PMID 39013885, 2024). "Specifically, we suggested that the SMAD complex (SMAD2/3/4) positively interacts with OCT4 (POU5F1), one of the essential markers of cancer stemness, as indicated by network analysis." (PMID 38245623, 2024). "In PDAC, CAF-released TGF-β has been demonstrated to contribute to cancer progression and gemcitabine resistance by upregulating the expression of ATF4 via the SMAD2/3 axis." (PMID 39518142, 2024). "The findings showed that deletion of VEGFA resulted in increased expression of PTEN, an inhibitor of pathways that promote cancer, as well as decreased expression of the members (MEK1/2 and AKT) of MAPK and the member (SMAD2) of TGFβ signaling pathways." (PMID 39457390, 2024). "Then, miR-148a targeted the SMAD2-3′UTR, leading to a decreased expression of SMAD2, which inhibited TGFβ/SMAD2 signaling and attenuated the cancer stem cell (CSC)-like properties, suggesting a new approach for the treatment of human cancers." (PMID 36838754, 2023). "TGF-β-induced SMAD2 phosphorylation was further enhanced in NEDD4L-silenced cancer cells, while NEDD4L overexpression severely impaired the TGFβ-induced phosphorylation of SMAD2." (PMID 37568787, 2023). "lncRNAs, such as MIR22HG, interact with SMAD2 to inhibit the TGF-β pathway and reduce the EMT of cancer cells." (PMID 36927770, 2023). "Inhibited phosphorylation of YAP/TAZ led to the accumulation of YAP/TAZ and Smad2/3 in the nucleus and promoted EMT of cancer cells." (PMID 38071381, 2023). "These docking results suggests a significant association of binding affinities between the interaction of Imiquimod and TGF-βbeta; signaling targets (Smad2, GATA2, and MAFG) which are mainly involved in the metastaticproperty in cancer cells." (PMID 37822834, 2023). "Another study found that MSCs accelerated the development of gastric cancer by secreting TGF-β1, which triggered the SMAD2/3 pathway and the lncRNA MACC1-AS1/miR-145-5p/fatty acid oxidation (FAO) axis in cancer cells." (PMID 38022534, 2023). "Propolin G has been designated as having anti-cancer activity through apoptotic induction and liver protection ability by attenuating the TGF-β-regulated Smad2/3 signaling pathway." (PMID 35163593, 2022). "We described herein the dichotomous role of SMAD2 and SMAD3 in the ability of cancer cells to form invadopodia and to produce spontaneous metastasis." (PMID 35681731, 2022). "TGF-β exerts complex and pleiotropic effects in cancers, notably via the activation of SMAD pathways, predominantly SMAD2/3/4." (PMID 36207615, 2022). "SMAD2 expression correlated negatively and SMAD3 expression positively with the invasive capacity of cancer cells, both in vitro and in vivo." (PMID 35681731, 2022). "Cytoplasmic ASPN interacts with Smad2/3 to promote its translocation to the nucleus and activates the TGF-β/Smad2/3 signaling pathway to promote EMT and proliferation in various cancer cells." (PMID 36011263, 2022). "Although a growing body of evidence indicates that each SMAD can play distinct roles both in vitro and in vivo, very few studies have concomitantly compared the individual roles of SMAD2 and SMAD3 in cancer progression." (PMID 35681731, 2022).
cancer (continued). "For cancer cells, Vimentin consequently led to metastasis and immune escape through the expression of PD-L1 in LUAD by triggering the TGF-β/SMAD2 signaling." (PMID 36119068, 2022). "Samples were grouped in “Healthy” and “Cancer” based on their saliva-derived exosomal miRNA profile, which was further found to be involved in RAS/MAPK, NF-κB complex, Smad2/3, and IFN-α signaling." (PMID 35899209, 2022). "To compare the impact of the modulation of SMAD2 or SMAD3 expression on the invasive properties of cancer cells, we used HT-1080 and MDA-MB-231 cells overexpressing shRNA directed against SMAD2 or SMAD3." (PMID 35681731, 2022). "Some of the related pathways are usually altered in some types of cancer as Beta-catenin independent WNT-signaling, SMAD2/SMAD3, tight junction, ABC transporters, etc.24–27." (PMID 33649335, 2021). "In vitro studies on breast cancer cells indicated asporin suppressed TGF-β1-mediated SMAD2 phosphorylation, EMT, and cancer stem cell signature." (PMID 33614646, 2021). "miR-3613-3p was shown to inhibit the growth of TNBC cell lines by targeting SMAD Family Member 2 (SMAD2) and Enhancer of Zeste Homolog 2 (EZH2), two important genes that implicate cell proliferation and cancer growth." (PMID 34439268, 2021). "The TGF-β1 activates Smad2/3, Akt/GSK-3β/β-catenin, NF-kB, ERK, JNK, and the p38 MAPK signaling pathway in cancer cells." (PMID 33849537, 2021). "Migration of epithelial carcinoma cells can be promoted through multiple core cancer pathways, including the JAK1/2-STAT3/5, β-Catenin/WNT, RAS/RAF-ERK1/2 or TGF-β/SMAD2/3 pathways." (PMID 33465556, 2021). "In consequence, syntenin increases TGF-β1-induced Smad2/3 activation and EMT transition in cancer metastasis." (PMID 33637682, 2021). "Western blot showed that incubation of cancer cells with Magnolol and TGF-β1 simultaneously markedly decreased the levels of E-cadherin and phosphorylation of Smad2/3 compared with incubation with TGF-β1 alone." (PMID 33344246, 2020). "Then, we immunohistochemically detected the expression of SMAD2 and EZH2 in 20 pairs of TNBC samples and paired paracancer specimens and found that the expression levels of SMAD2 and EZH2 were significantly increased in cancer tissues." (PMID 33330073, 2020). "Via Smad2/Smad3 and transforming growth factor β (TGF-β) signaling, increased FOXP1 expression restrained CD8+ T cells from proliferation and activation in cancer." (PMID 32719717, 2020). "As R-SMAD proteins, the impacts of SMAD2 and SMAD3 on cancer initiation and progression were widely investigated." (PMID 32746934, 2020). "To further prove the role of TGF-β2 in EMT under acidic conditions, we silenced Smad2/3 and confirmed a dramatic reduction in SNAIL1 and ZEB1 in 6.5/cancer cells." (PMID 31974393, 2020). "SMAD Family Member 2 (SMAD2) and Enhancer of Zeste Homolog 2 (EZH2) are two important genes that play roles in the cell cycle transition and cancer proliferation." (PMID 33330073, 2020). "As a member of the SMAD family, SMAD2 plays a key role, together with SMAD3 and SMAD4, in TGF-β signaling and cancer progression." (PMID 31762811, 2019). "Since it has been demonstrated that Smad2/3 and E2F1 are critical mediators of TGF-β-induced EMT in both normal and cancer cells, we examined the effects of TGF-β1 and miR-20b-5p on Smad2 phosphorylation and E2F1 expression." (PMID 32010624, 2019). "In a cancer context, Syntenin-1 was demonstrated to positively regulate TGF β1 mediated SMAD2/3 activation and EMT transition and to enhance cell surface expression of TGFR1." (PMID 31783876, 2019). "Previous research has shown that Smad2/3 and E2F1 are critical mediators of the effects of TGF-β in both normal and cancer cells." (PMID 32010624, 2019). "In cancer cells, upon the binding of free-active TGF-β1 to the receptor TGF-βR, SMAD2/3 are translocated to the receptor complex and phosphorylated." (PMID 31464606, 2019).
cancer (continued). "Here we gave an alternative explanation of ASPN’s pro-motility role in cancer cells, i.e. activation of TGF-β/Smad2/3 signaling from inside cells." (PMID 30728352, 2019). "In a study of 46 normal and cancer cell lines, BMP2 was shown to induce SMAD2/3 signaling preferentially in embryonic and transformed cells." (PMID 29416020, 2018). "HOXB9 was previously reported to regulate cancer progression, by targeting EMT via the transforming growth factor-β1/Smad2/Slug signaling pathway." (PMID 29724991, 2018). "When cancer cell lines A549, H460, or 4T1 were treated with TGF-β1, increased Smad2 phosphorylation (pSmad2) was observed." (PMID 29796175, 2018). "Western blotting analysis indicated that the levels of phosphorylated of Smad2 protein (p-SMAD2), p-SMAD3 and p-SMAD4were significantly elevated in CAF-CM and TGF-β1-treated cancer cells, suggesting that CAFs activated the TGF-β1/SMAD signaling pathway." (PMID 29325547, 2018). "In cancer, the binding between UCA1 promoter core region and transcription factors or complex (C/EBPα, Ets-2, TAZ/YAP/TEAD and SMAD2/3) can enhance UCA1 promoter activity and gene expression." (PMID 28423704, 2017). "In cancer cells harboring KRASmt, NRP1 down regulation promotes tumorigenesis through the suppression of SMAD2 pathway." (PMID 29018205, 2017). "Lastly, our method not only identified the known cancer genes but also detected the potential rare drivers (PTPN6 in THCA, SRC, GRB2 and PTPN6 in KIRC, MAPK1 and SMAD2 in HNSC)." (PMID 28938536, 2017). "Interacting genes included well-established cancer-connected genes such as DNMT3A, SMAD2, MTCP1 and TLE4 (refs 36, 37, 38, 39)." (PMID 28534499, 2017). "EGF-induced nuclear co-localization of phospho-Smad2/3 and Snail and cancer cell migration were inhibited by pretreatment with an ERK1/2 inhibitor, PD98059 and a phospho-Smad2 inhibitor, SB203580." (PMID 27829223, 2016). "Here we investigated the role of DLX2 in association with radiation-induced epithelial to mesenchymal transition (EMT) and stem cell-like properties and its regulation by Smad2/3 signaling in irradiated A549 and MDA-MB-231 human cancer cell lines." (PMID 26799321, 2016). "Knockdown of Smad2/3 expression suppressed EGF-induced expressions of Snail, vimentin, fibronectin, and cancer cell invasion, suggesting an acquisition of the mesenchymal and migratory phenotype in less aggressive MCF-7 cells." (PMID 27829223, 2016). "For example, genes with Motif 1 in Molecular Mechanisms of Cancer pathway include MAPK1, BRAF, SMAD2, FZD5, FZD8, NOTCH1 and LRP1, whereas genes with Motif 2 and/or Motif3 in the same pathway include LRP5, LRP6, MDM2, CTNND1, SMAD3, SMAD4 and SMAD7." (PMID 26040697, 2015). "After verifying the biological meaning of the low-cost paths, the signal TGFβ1- TGFβR1- SMAD2/3- SMAD4- AR-OCIAD2 was discovered and explained TGFβ's stimulation on OCIAD2 expression in cancer." (PMID 24949437, 2014). "Collectively, these data suggested that HRG-β1 induced cancer cell migration and invasion through induction of EMT via PI3k/Akt-phospho-Smad2-Snail signaling pathway." (PMID 23937725, 2013). "Some signaling pathways, such as notch, CXCL12-CXCR4, Oct4-TCL1-AKT, PTEN/P13K/Akt, β-catenin/Tcf, AhR, and HIF-2α with TGF-β/Smad2 are related to the ABCG2 status as a marker of stem cells or stem-like cancer cells." (PMID 24312054, 2013). "We found two major types of complexes that are affected by miRNAs during cancer progression; the first contains SMAD3, SMAD2, SMAD4, SMAD6, FOXO1, HOXC8, and SKIL, which are connected to AKT1, which is in turn a key modulator of TGF-B signaling pathway." (PMID 24391925, 2013).
cancer (continued). "Aliquots of total protein extracts from MVEC cells exposed for 2.5 hours to CM of cancer cells were analyzed by Western blot probed for p-SMAD1/5 and p-SMAD2." (PMID 23226264, 2012). "While activated Smad2/3 complexes promote EMT, the inhibitory Smad7 prevents the transition of cancer cells towards a mesenchymal phenotype." (PMID 21747928, 2011). "Recently, knockdown GRP78 or Cripto disrupts of the Cripto binding to cell surface GRP78 in cancer cells inhibits oncogenic signaling via MAPK/PI3K and Smad2/3 pathways." (PMID 20979610, 2010). "We show that CystC inhibits the stimulation of Smad2 phosphorylation by TGF-β and the subsequent induction of reporter gene expression in normal and cancer MECs." (PMID 16168131, 2005). "Additionally, upregulation of SMAD2 and SMAD3 expression has been observed in the live cancer cell upon exposure to L. sativum extracts." (PMID 41210686, 2025). "Studies have reported that miR-27a and miR-155 target SMAD2 and SMAD4, which may lead to downregulation of TGF-β1 in some cancers, which is important for modulating the antitumor effects of the pathway in early-stage tumors." (PMID 40943648, 2025). "Smad2/3 activation typically reflects TGF-β signaling, which is known to have dual roles in cancer." (PMID 41020812, 2025). "We previously reported that the myofibroblastic trait is stably maintained in human breast CAFs due to the establishment of TGF‐β‐Smad2/3 autocrine signaling without ongoing interactions with cancer cells in culture." (PMID 40644310, 2025). "The ALK5/p38 axis of TGFβ signaling phosphorylates and stabilizes the ΔNp63 protein, whereas activation of the SMAD2/3 axis induces the formation of the ΔNp63-p300 complex, leading to H3K27 acetylation and activation of transcription, promoting cancer cell stemness and invasiveness." (PMID 39180088, 2024). "The downregulation of TGFBR1 and p-SMAD2/3 suggests the suppression of TGF-β signaling, which may contribute to the reversal of CAF activation and the inhibition of cancer-promoting effects." (PMID 38910148, 2024). "Inhibitors targeting TGF-β and Smad2/3 signaling can stimulate CEC differentiation and promote their maturation, thereby neutralizing their suppressive effects, and have been proven effective in mouse models of cancer." (PMID 39474425, 2024). "Mechanistically, NSDHL knockdown impaired the cancer stemness characteristics of BCSCs by suppressing TGF-β signaling, which in turn decreased the secretion of TGF-β 1 and TGF-β3, inactivated Smad2 and Smad3, and downregulated the expression of SOX2 and NANOG, key regulators of cancer stemness." (PMID 39516821, 2024). "Importantly, SMAD2 and SMAD3 are directly activated by TGFβ receptors, and bufalin exerted inhibitory effects on the SMAD2 and SMAD3 in cancer cells." (PMID 36903477, 2023). "Here, platelet TGFβ1 is a general driver of cancer cell epithelial-to-mesenchymal transition (EMT) via activation of the Smad2/3 and NF-kB pathways, and of HCC growth both in vitro and in vivo, where it also suppresses cancer cell Krueppel-like factor 6 (KLF6) expression." (PMID 38116017, 2023). "Importantly, we revealed that, in macrophages transfected with SMAD2 siRNA, the effects of FAM198B overexpression on macrophage-promoted cancer cell migration and invasion were impeded." (PMID 35587159, 2022). "Our results suggesting that SARA is an active participant in both SMAD2-inhibitory and SMAD3-stimulatory effects on cancer cell invasion are consistent with the possibility that the targeting of SARA/SMAD binding would be unlikely to provide significant therapeutic benefits for cancer patients." (PMID 35681731, 2022). "CCT6A was discovered to be an inhibitor and direct binding protein of SMAD2, and it was shown that CCT6A may block the function of SMAD2 in NSCLC cells and enhance cancer cell metastasis." (PMID 36588537, 2022).